GSDME (gasdermin E)
Diseases named in the same sentence as GSDME in open-access papers (continued):
Sharing a sentence is not in itself a finding about the gene and the disease.
GSDME also shares sentences with these, for which no sentence is quoted: Hearing impairment (13 papers); hydronephrosis (5); Crohn disease (3); asthma (2); breast adenocarcinoma (2); kidney cancer (2); liver disease (2); lobular adenocarcinomas (2); oesophageal cancer (2); Acute hepatic failure (1); acute liver failure (1); acute respiratory distress syndrome (1); adenoma (1); alopecia (1); anaplastic thyroid cancer (1); autoimmune disease (1); cardiomyopathies (1); chronic asthma (1); chronic kidney disease (1); colon adenocarcinoma (1); corneal infection (1); distal renal tubular acidosis (1); dysplastic nevi (1); endothelial dysfunction (1); endotoxemia (1); familial Mediterranean fever (1); frontotemporal dementia (1); human papillomavirus infection (1); Hyperkeratosis (1); Hypertension (1).
A further 30 diseases each share a sentence with GSDME in 1 paper.